DSG3 (desmoglein 3)
Diseases named in the same sentence as DSG3 in open-access papers (continued):
Sharing a sentence is not in itself a finding about the gene and the disease.
pemphigus (continued). "In order to verify the pathogenic activity of anti-Desmocollin 3 (DSC3) antibodies, we developed an active disease model of pemphigus expressing anti-DSC3 autoantibodies or anti-DSC3 and anti-DSG3 antibodies." (PMID 31275323, 2019). "Perhaps, the most effective IVIg batches contained Nab to M3AR and/or other known pemphigus self-antigens, such as Dgs1 or Dsg3, whose binding to non-functional epitopes of the targeted molecules protected them from pathogenic AuAbs." (PMID 40120680, 2025). "There are numerous case reports of individuals with positive antibodies to Dsg1 and Dsg3 antigens without a pemphigus phenotype." (PMID 40098967, 2025). "Autoantibodies in pemphigus primarily target Dsg1 and Dsg3, with additional antibodies against desmosomal and non-desmosomal proteins contributing to disease complexity." (PMID 40372624, 2025). "In pemphigus, the presence of circulating anti‐Desmoglein‐1/3 (Dsg1 and Dsg3) autoantibodies in individuals without skin lesions indicates that additional factors, potentially including local immune responses, influence disease manifestation." (PMID 40051023, 2025). "We did not detect DSG3-Fc cleavage after incubation with either pemphigus autoantibodies or AC1-IgG." (PMID 37450050, 2023). "Another model using mouse major histocompatibility complex (MHC) class II‐deficient HLA‐DRB1*0402 transgenic mouse helped analyze the interaction between human Dsg3 peptide and pemphigus‐related HLA molecules without obtaining Dsg3‐specific T cell clones." (PMID 36539957, 2023). "Moreover, in a pemphigus mouse model, administration of anti-CD154 mAb blocked anti-Dsg3 IgG production and prevented blister formation." (PMID 36203615, 2022). "Regardless of pemphigus subtype, autoantibody titre negativity at clinical remission in patients classified based on their anti‐Dsg1 and anti‐Dsg3 profile at diagnosis and BSA were useful tools in predicting relapse." (PMID 34288016, 2022). "We conclude that, although our model has only bi-specific anti-DSG1/DSG3 scFv, some ultrastructural hallmarks of desmosome morphology following Px4-3 binding are reproduced in our HSOC model, reflecting the lesional skin of pemphigus patients." (PMID 36452895, 2022). "Pemphigus is a chronic autoimmune skin blistering disease, characterized by acantholysis and by the production of autoantibodies directed against the structural desmosomal proteins desmoglein 1 (DSG1) and/or DSG3." (PMID 36452895, 2022). "The Dsg1/Dsg3 compensation theory explains why skin and mucosa are not equally affected by the target antigen specific autoantibodies in different pemphigus forms." (PMID 34447768, 2021). "A deeper analysis of the active pemphigus mouse model revealed that, in these mice, a single Dsg3-specific CD4+ T-cell clone was able to induce a clinical phenotype in recipient mice by activating Dsg3-reactive B cells." (PMID 35187073, 2021). "It was shown that activation of Src was detectable only when PV-IgG fractions contained antibodies against Dsg3 but not when pemphigus foliaceus (PF) autoantibodies against Dsg1 were applied." (PMID 31024527, 2019). "One potential limitation of Dsg3 CAAR-T-cell therapy in pemphigus IgG-driven autoimmunity not only against Dsg3 but also against Dsg1." (PMID 31293582, 2019). "Indeed, DSG1-positive and DSG3-positive B cells were detectable in HD, although at a lower frequency than in the 20 patients with active pemphigus (DSG1 positive 0.11 vs. 0.20%, p < 0.001; DSG3 positive 0.10% vs. 0.20%, p < 0.001)." (PMID 31440235, 2019). "Because of the different expression of the pemphigus autoantigens (Dsg1 and Dsg3) in the cornified and non-cornified epithelium, skin and mucosae are differentially affected by anti-Dsg IgG autoantibodies." (PMID 31293582, 2019). "There have also been reports of high Dsg1 and Dsg3 ELISA values despite the absence of disease activity as well as low levels despite a relapse of pemphigus." (PMID 29872685, 2018).
pemphigus (continued). "The serological diagnosis of pemphigus relies on the detection of IgG autoantibodies directed against the epithelial cell surface by indirect immunofluorescence (IIF) on monkey esophagus and against desmoglein 1 (Dsg1) and Dsg3 by ELISA." (PMID 29740444, 2018). "Neither was observed in pemphigus between the proportion of CD19hi B cells and anti-Dsg1 or anti-Dsg3 autoantibodies." (PMID 29066741, 2017). "Dsg1 and Dsg3 ELISAs have high sensitivity and specificity (98–100%) for disease, indicating that pemphigus does not occur in the absence of anti-Dsg antibodies and, furthermore, disease activity correlates with serum autoantibody titer." (PMID 28184292, 2017). "In pemphigus, serum anti-Dsg1 and Dsg3 autoantibodies levels were not related to peripheral CD19hi B cells either." (PMID 29066741, 2017). "A 2018 study found that almost half of subjects in a population in Amazonian Peru had positive anti-Dsg1 antibodies and approximately 25% had positive anti-Dsg3 antibodies in the absence of pemphigus lesions, highlighting the role of environmental and ethnographic factors." (PMID 40098967, 2025). "As the PF-anti-Dsg3(-) group consisted of treatment-naïve patients, it is not known whether anti-Dsg3 would be produced during pemphigus evolution." (PMID 38851894, 2024). "In addition, mice with imiquimod‐induced acute thymic involution also allow Dsg3‐specific T cell development in the thymus but do not show clinical symptoms of pemphigus, despite the expression of Dsg3 antigen in their peripheral tissues." (PMID 36539957, 2023). "Another interesting finding from this study is that DSG3 plays a significant role in MHC complex assembly and binding (GO:0002399, GO:0002501, GO:0002396, GO:0042613, GO:0042611), pointing to its involvement in immune regulation, as demonstrated in pemphigus autoimmune blistering disease." (PMID 38067138, 2023). "Collectively, these data suggest that DSG3 inhibits YAP and promotes p‐YAP expression indirectly via inhibition of EGFR signalling and its downstream Hsp27 and c‐Jun in oral keratinocytes, the findings agreed with what has been characterised for DSG3 from pemphigus research." (PMID 35000271, 2022). "Patient classification based on anti‐Dsg1 and anti‐Dsg3 autoantibody positivity at diagnosis, regardless of pemphigus subtype and subsequent assessment of antibody titres at clinical remission, may be of use in predicting relapses." (PMID 34288016, 2022). "Moreover, ADAM10 inhibition was shown to be protective in a murine pemphigus model when antibodies against Dsg1 and Dsg3, but not Dsc3, were present in the patient sera." (PMID 35844545, 2022). "Dsg3 and Dsg1 are the major target antigens in pemphigus, but in the last 20 years, new relevant findings have demonstrated the role of non-Dsg autoantibodies in pemphigus cell-cell detachment even acting synergistically when Dsg autoantibodies are absent." (PMID 34567003, 2021). "In addition, frequencies of Th17 and Tfh17 cells in the blood of patients with pemphigus correlate with levels of Dsg-specific CD19+CD27+ memory B cells, while patients with acute pemphigus exhibit higher levels of Dsg3-autoreactive Tfh17 cells." (PMID 35187073, 2021). "We hypothesize that levels of IgG autoAbs against TPO and/or AChRs from patients with pemphigus will not be correlated with clinical disease activity or levels of IgG autoAbs against DSG1 or DSG3." (PMID 32555697, 2020). "Therefore, its pathogenic correlation has no direct connection with the level of anti-DSG1/DSG3 IgG nor anti-BP180/230 IgG in the serum of pemphigus and SABD patients, respectively." (PMID 32235430, 2020). "Anti-Dsg3 autoantibody values did not differentiate between pemphigus severity classes." (PMID 33129291, 2020). "However, the level of anti-Dsg-1 and anti-Dsg-3 antibodies, which play an important role in the pathogenesis of pemphigus did not present any significant difference among each period." (PMID 30083474, 2018).
pemphigus (continued). "Thus, some authors claim that the combination of a Dsg1-rich substrate, such as guinea pig esophagus or human skin, and a Dsg3-rich substrate, such as monkey esophagus, is crucial prerequisite to increase the sensitivity of IIF when screening the sera of pemphigus patients." (PMID 30386780, 2018). "The Dsg3 recombinants of the present studies may not contain all the conformational epitopes that are relevant in the immune pathogenesis of pemphigus." (PMID 20671975, 2010). "In addition, Dsg3‐specific Tfh cells were detected using I‐Ab tetramer with Dsg3 (516–530 aa) peptide highly expressed ICOS, and ICOS blockade reduced anti‐Dsg3 antibody production in the model, demonstrating pivotal roles of Dsg3‐specific ICOS+CXCR5+PD‐1+ Tfh cells in the pemphigus mouse model." (PMID 36539957, 2023). "Pemphigus is a group of chronic, rare, potentially life-threatening AIBD of the skin and/or mucous membranes characterized most commonly by autoimmunity against desmoglein (DSG) proteins, namely, DSG3 alone, DSG1 alone, or both DSG3/DSG1, but other antibodies may be involved in immunization." (PMID 37885886, 2023). "The presence of anti‐Dsc3 autoantibodies was sufficient to determine the appearance of a pathological phenotype relatable to pemphigus, but with features not completely superimposable to those observed in the Dsg3 active model, suggesting that the Dsc3 active model might mimic atypical pemphigus." (PMID 36578135, 2023). "In addition to Dsg3 and Dsg1, several other organ-specific non-Dsg autoantibodies in pemphigus patient sera could be involved in an intermolecular ES phenomenon." (PMID 29719538, 2018). "While not currently a standard pemphigus therapy, INE effectively reduced Dsg1 and Dsg3 levels to normal, resolved symptoms, reduced Pemphigus Disease Activity Index scores, and allowed prednisone tapering to 5 mg per day." (PMID 41362865, 2026). "Although available tests for pemphigus-related autoantibodies (including BP180, BP 230, Dsg1, and Dsg3) were negative, the diagnosis of PNP was finally confirmed by the presence of pelvic tumor and positive tests of indirect immunofluorescence on rat bladder." (PMID 39473502, 2024). "Screening for pemphigus-related autoantibodies, including BP180, BP 230, Dsg1, and Dsg3, yielded negative results." (PMID 39473502, 2024). "Dsg3-CAART therapy has been reported to lead to serological and histological improvements in experimental pemphigus mice without detectable off-target toxicity." (PMID 35783635, 2022). "Adapted from that strategy, Dsg3 chimeric autoantibody receptor T cell (Dsg3-CAART) therapy has been reported to result in serological and histological improvements in experimental pemphigus mice without detectable off-target toxicity." (PMID 31130959, 2019).
pemphigus vulgaris (124 papers, 2006 to 2026). Pemphigus is a group of chronic autoimmune skin diseases characterized by blister formations on the outer layer of the skin and the mucous membranes. "In the bullous autoimmune disease pemphigus vulgaris (PV), autoantibodies directed mainly against desmoglein 1 (Dsg1) and Dsg3 cause loss of desmosomal adhesion." (PMID 40299565, 2025). "The first described CAAR uses a portion of desmoglein 3 (Dsg3) as its extracellular domain to treat pemphigus vulgaris (PV), an autoimmune blistering disease caused by autoantibodies against the keratinocyte adhesion protein Dsg3." (PMID 39821376, 2025). "Background and Objectives: Pemphigus vulgaris (PV) is a rare autoimmune blistering disease caused by IgG au-toantibodies against desmoglein 1 and/or desmoglein 3, leading to flaccid blisters on the skin and mucous membranes." (PMID 41597317, 2025). "In pemphigus vulgaris, an autoimmune disease of the epidermis, IgG autoantibodies directed against desmosomal adhesion proteins, especially desmoglein-3 and -1, cause loss of keratinocyte adhesion." (PMID 39450168, 2024). "Dsg3 is of special biomedical relevance because it is the autoantigen in the severe blistering skin disease pemphigus vulgaris and it is well established that loss of Dsg3 adhesion significantly contributes to pemphigus vulgaris pathogenesis." (PMID 36602635, 2023). "Pemphigus vulgaris (PV) is a potentially lethal autoimmune bullous skin disorder caused by IgG autoantibodies against desmoglein 3 (Dsg3) and Dsg1." (PMID 37174740, 2023). "Among the different phenotypic variants encompassing this disease, Pemphigus vulgaris (PV) and Pemphigus foliaceus (PF), caused by the presence of autoantibodies against the desmosomal cadherins desmoglein 3 (DSG3) and 1 (DSG1), are the most common forms." (PMID 35806044, 2022). "For instance, loss of DSM adhesion via pemphigus vulgaris autoantibodies targeting Dsg3 involves impairment of the actin cytoskeleton and is restored by activating RhoA63." (PMID 31942240, 2019). "Pemphigus vulgaris (PV) usually is associated with autoantibodies against Dsg3 whereas pemphigus foliaceus (PF) patients present autoantibodies against Dsg1." (PMID 31178865, 2019). "Autoantibodies against desmoglein (Dsg) 1 and Dsg3 primarily cause blister formation in the autoimmune disease pemphigus vulgaris (PV)." (PMID 31024527, 2019). "DSG3 is one of the component in the desmosome, and disorder of DSG3 is known to be related with pemphigus vulgaris via loss of cell-to-cell adhesion by autoantibodies against DSG3." (PMID 29758011, 2018). "Desmoglein 3 (DSG3) is highly expressed in lung squamous cell carcinoma, while it is well-known that anti-DSG3 antibodies cause pemphigus vulgaris, an autoimmune disease." (PMID 30239818, 2018). "Pemphigus vulgaris (PV) is another severe autoimmune bullous skin disease and is primarily associated with IgG against desmoglein 3 (dsg3), a desmosomal adhesion protein." (PMID 29686678, 2018). "Pemphigus vulgaris (PV) is an autoimmune bullous disease caused by acantholysis of keratinocytes due to pathogenic desmoglein-3 autoantibodies." (PMID 25128193, 2014). "BP180-Abs are associated with BP while desmoglein antibodies with pemphigus vulgaris (Dsg3-Abs) and pemphigus foliaceus (Dsg1-Abs)." (PMID 23781320, 2013). "Pemphigus vulgaris (PV) is an autoimmune epidermal blistering disease caused by autoantibodies directed against the desmosomal cadherin desmoglein-3 (Dsg3)." (PMID 23226536, 2012). "A disorder related to DSG3 is pemphigus vulgaris, an autoimmune disease associated with the production of autoantibodies against PVA responsible for the loss of cell-to-cell adhesion." (PMID 19997107, 2010). "The protein encoded by DSG3 is the autoantigen for the autoimmune skin disease pemphigus vulgaris and this gene is expressed primarily in skin." (PMID 19772629, 2009).
pemphigus vulgaris (continued). "Pemphigus vulgaris (PV) is a severe autoimmune blistering disorder characterized by the presence of pathogenic autoantibodies directed against desmoglein-3 (Dsg3), involving specific DR4 and DR6 alleles in Caucasians and DQ5 allele in Asians." (PMID 16426456, 2006). "Importantly, the autoimmune disease pemphigus vulgaris is caused by autoantibodies targeting desmoglein-3, resulting in blistering and erosions of the skin and mucosae (accordingly, desmoglein-3 is also known as “pemphigus vulgaris antigen”)." (PMID 37835579, 2023). "Pemphigus vulgaris (PV) is an autoimmune disease that manifests as flaccid blistering of the mucosa and the epidermis, caused mainly by IgG1 and IgG4 autoantibodies against the desmosomal cadherins, especially Dsg3 and Dsg1." (PMID 35326398, 2022). "Pemphigus vulgaris (PV) is an autoimmune disease characterized by blistering sores on skin and mucosal membranes, caused by autoantibodies primarily targeting the cellular adhesion protein, desmoglein-3 (Dsg3)." (PMID 31340153, 2019). "Pemphigus vulgaris (PV) is a potentially lethal autoimmune disease characterized by blister formation of the skin and mucous membranes and is caused by autoantibodies against desmoglein (Dsg) 1 and Dsg3." (PMID 29922278, 2018). "However, DSG3 is a molecule associated with pemphigus vulgaris (PV), a severe autoimmune blistering disease affecting skin and mucosa, and it is known that anti-DSG3 autoantibodies are involved in the onset of the disease." (PMID 30239818, 2018). "In pemphigus vulgaris (PV), IgG autoantibodies against Dsg3 cause a profound blistering of the skin and mucosal epithelia, whereas in pemphigus foliaceus, IgG autoantibodies against Dsg1 cause a blistering phenotype restricted to the skin (for a review, see9, 10)." (PMID 27346727, 2016). "Pemphigus vulgaris (PV) is a rare, autoimmune, potentially fatal mucocutaneous bullous disease in which pathogenic autoantibodies are directed against the keratinocyte cell surface molecules desmoglein 3 (Dsg3) and to a lesser extent Dsg1." (PMID 24298388, 2013). "Pemphigus vulgaris (PV) is a life-threatening autoimmune blistering disease caused by IgG autoantibodies (auto-Ab) against the extracellular domain (ECD) of desmoglein 3 (Dsg3) and Dsg1, desmosomal adhesion molecules present on epidermal keratinocytes." (PMID 20671975, 2010). "The association of an intronic SNP in the gene DSG3 (desmoglein 3 (pemphigus vulgaris antigen)) may also be indicative of a neuromelanin related effect on onset age of PD." (PMID 19772629, 2009). "To further evaluate whether the observed DSG2 cleavage is specific for autoantibodies from AC patients, we tested whether autoantibodies causing the autoimmune blistering skin disease pemphigus vulgaris (PV), which are directed primarily against DSG3, also induce DSG2 cleavage." (PMID 37450050, 2023). "Therefore, in this study we investigated the roles of Dsg2 and Dsg3, the latter of which is known to be essential for keratinocyte adhesion based on its autoantibody-induced loss of function in the autoimmune blistering skin disease pemphigus vulgaris (PV)." (PMID 23326495, 2013). "Interestingly, DSG3 deficiency is linked to the blistering disease Pemphigus Vulgaris, in which autoantibodies directed against DSG3 in the serum of patients attack the protein and compromise desmosomal function, leading to severe blistering of the oral mucosa." (PMID 23185521, 2012). "In preclinical studies on pemphigus vulgaris, T cells were engineered to express the autoantigen desmoglein 3 (Dsg3) on their surface, enabling precise recognition and destruction of B cells producing anti-Dsg3 autoantibodies." (PMID 41596556, 2026). "For example, CAAR-T cells engineered to recognize desmoglein-3 (Dsg3) have demonstrated efficacy in eliminating Dsg3-specific B cells, ameliorating symptoms in pemphigus vulgaris (PV)." (PMID 41200159, 2025).